LEP (leptin)
Diseases named in the same sentence as LEP in open-access papers (continued):
Sharing a sentence is not in itself a finding about the gene and the disease.
Obesity (continued). "The relative role of serum vitamin D levels and varying levels of adiponectin and leptin in the association between obesity and MS." (PMID 35911285, 2022). "Obesity is implicated in a mutation in the leptin/melanocortin pathway in the central nervous system, which plays a role in regulating body energy haemostasis." (PMID 35291277, 2022). "Recently, it has also been reported that C. minuta DSM33407 protected from diet-induced obesity and regulated associated metabolic markers such as glycemia and leptin in a diet-induced obesity mouse model." (PMID 35115054, 2022). "In majority of studies, increased levels of CFD and LEP have been linked to obesity associated BC progression via enhanced TGFβ signalling and MMP modulation." (PMID 34997107, 2022). "Obesity-associated alterations in adipokine concentrations, namely leptin and adiponectin, underpin the development of adipose tissue dysfunction, thus supporting an environment conducive to cardiometabolic disease." (PMID 35654771, 2022). "We investigated leptin and adiponectin as well as IR and their association with thyroid hormone in both lean and hypothyroid children and adolescents with obesity." (PMID 35501770, 2022). "Obesity has also been associated with leptin resistance, which can result in increased circulating leptin levels but decreased leptin signaling." (PMID 34982778, 2022). "These in vitro observations are consistent with the improved glucose tolerance induced by fluoxetine administration to ob/ob mice, a leptin‐deficient model of obesity and hyperglycaemia." (PMID 35676820, 2022). "Several other investigations have confirmed the association between obesity and the methylation status of LEP and ADIPOQ, which has been proposed to promote obesity-associated insulin resistance and metabolic derangements." (PMID 35163268, 2022). "In the current study, we characterized the effects of a global GLUT6 knockout in a more severe model of obesity and beta cell compensation: the leptin-deficient ob/ob mice." (PMID 36077188, 2022). "Clinical studies in patients with obesity have revealed that mutations in leptin, pro-opiomelanocortin (POMC), and melanocortin 4 receptor (MC4R) are positively associated with hyperphagia, hyperinsulinemia, and excessive adiposity." (PMID 35757435, 2022). "Zinc deficiency not only leads to the decrease of leptin, but also leads to unhealthy eating behaviors such as taste disorder, partial eclipse, and different diet, which leads to obesity." (PMID 35565860, 2022). "Variations in leptin, adiponectin, and visfatin are also linked with obesity and systemic inflammation." (PMID 36231983, 2022). "Mechanism-oriented studies in mice show that high NaCl intake can stimulate aldose reductase–fructokinase pathway in both liver and hypothalamus, causing endogenous fructose production, subsequent leptin resistance, and hyperphagia, resulting in obesity." (PMID 36097199, 2022). "In humans, mutations in the coding sequence or at splice sites of LEP cause severe early-onset obesity due to the leptin protein’s inability to signal via its receptor." (PMID 35886710, 2022). "Yet, it is known that this deletion causes the loss of exon 2 of the LEP gene and thus a congenital leptin deficiency with resultant obesity." (PMID 36121795, 2022). "Even more discouraging for those believing leptin was going to be the answer to the “obesity epidemic” was the limited number of people identified with a deficiency in leptin production." (PMID 35662925, 2022). "Studies on rodents and humans provide evidence that the majority of exercise induced favorable effects on obesity are linked to lower leptin levels and improve leptin resistance." (PMID 36225863, 2022). "One perspective is that increased leptin levels accompanying leptin resistance in obesity cause harmful effects on immune signal transduction." (PMID 36366398, 2022).
Obesity (continued). "Arguably, the DIO model is a better means of recapitulating the human obesity state versus the leptin deficient models which also can have developmental issues on immune and non-immune cell-types." (PMID 36776393, 2022). "The leptin-deficient ob/ob mouse and the leptin receptor deficient db/db mouse are the most commonly used genetically engineered animal models of obesity." (PMID 36140261, 2022). "This agrees with reported data where it is mentioned that obesity, insulin resistance, fatty liver, and low degree of inflammation (increased C-peptide and leptin with decreased concentration of adiponectin) cause a low diversity of the intestinal microbiota." (PMID 35036426, 2022). "Although some people with obesity hypo-secrete leptin, most have high endogenous hormone levels (a hallmark of obesity) and show a diminished response to leptin administration." (PMID 36411386, 2022). "Deficiencies in leptin or LepR signaling, or leptin resistance can develop in response to inflammation, endocrine disorders, lipodystrophy, or obesity, which progresses to glucose intolerance and insulin resistance." (PMID 35159237, 2022). "Serum leptin concentration increases with obesity, but obesity is associated with resistance to the effects of leptin." (PMID 35834069, 2022). "It is likely that obesity-associated factors, including leptin, converge to regulate metabolic pathways leading to a hormonal milieu conducive to tumor growth." (PMID 36230822, 2022). "A putative contributor to leptin and insulin resistance associated with diet-induced obesity is chronic inflammation triggered by saturated fats and rapid adipose tissue expansion." (PMID 34184629, 2022). "The EPIC-Heidelberg study demonstrated that the genotype AA of the LEP (rs7799039) gene is associated with the development of obesity." (PMID 36117520, 2022). "It is well known that an imbalance in the ratio between leptin and adiponectin is associated with obesity." (PMID 36397166, 2022). "Leptin resistance is a hallmark of obesity, featuring a high concentration of circulating and central leptin." (PMID 36465655, 2022). "It has been suggested that obesity is an independent risk factor for the development of goiter, associated with increased leptin secretion and stimulation of the hypothalamic-pituitary-thyroid axis." (PMID 36605940, 2022). "It is reported that mutations in the FTO gene raise blood levels of leptin, a known mediator or growth factor between obesity and colon cancer, which activates a variety of pathways associated with colon cancer." (PMID 36292657, 2022). "Given leptin’s key signaling roles in the regulation of metabolism and energy homeostasis, children with leptin gene mutations and other forms of congenital leptin deficiency develop severe hyperphagia, reduced energy expenditure and obesity." (PMID 36558383, 2022). "It is commonly known that low circulating levels of the leptin, as well as leptin resistance, are widely correlated with a higher risk of obesity and its aftermath." (PMID 35328503, 2022). "AN is a clinical sign that has been associated with obesity, IR, hormonal disorders, lipoinflammation mediated by leptin and adiponectin, the use of certain medications and supplements, and some types of cancer." (PMID 35386232, 2022). "Upon obesity, such as in leptin-deficient (ob/ob) mice, PPARγ and its target gene Fsp27 are activated in the liver to promote FA storage as lipid droplets." (PMID 36172518, 2022). "It is well known that obesity is associated with hyperleptinemia and leptin resistance due to changes in leptin transport across the blood-brain barrier, as well as in LEPRs or their isoforms." (PMID 35216509, 2022). "The POMC neurons and associated leptin–melanocortin pathway is currently a mainstay of obesity-based genetic research." (PMID 36012526, 2022).
Obesity (continued). "Recently, it has been reported that maintaining lower levels of leptin expression in animal adulthood protects against high-fat-induced obesity and associated metabolic disorders, and increases sensitivity to exogenous leptin." (PMID 36618698, 2022). "Obesity and diabetes often go hand in hand in clinical settings, and therefore animals that are deficient for leptin and the leptin receptor are an elegant way of modeling such a setting." (PMID 35628192, 2022). "When subgroup analysis was performed on obesity according to sex, the associations between LEP polymorphisms and leptin levels were also only significant among obese women in the dominant model." (PMID 36293132, 2022). "A recent study on obesity has demonstrated the role of SNPs in fat mass, obesity‐associated LEP, and LEP receptor genes." (PMID 35421277, 2022). "Adipocytokines, such as leptin and adiponectin, are adipose-tissue-derived molecules and have been associated with insulin resistance (IR), obesity, metabolic syndrome, atherogenesis, and acute cardiovascular events, leading to several metabolic outcomes." (PMID 36010082, 2022). "Serum leptin levels become dysregulated in fetal growth restriction, obesity, and pre-eclampsia, all conditions that elevate risk for life-long disease." (PMID 36005607, 2022). "CRP, IL-6, TNFα, and leptin are found to be elevated in individuals with obesity and are also strongly associated with the development of preeclampsia." (PMID 35348641, 2022). "Many monogenic neuroendocrine disorders involving the leptin pathway are recognized and associated with early onset obesity in childhood." (PMID 36232301, 2022). "Even though not frequent, the monogenic mutations form the predominant genetic reason for causing obesity and leptin resistance in early childhood, which contributes to childhood obesity." (PMID 35628271, 2022). "In case of the three genetic variants of CEPT, FTO and LEP genes, MAFs were higher in lean-normal body mass and showed obesity protective association." (PMID 36126070, 2022). "SNPs of the leptin pathway have been associated with the control of hunger and energy expenditure as well as with obesity and type 2 diabetes mellitus." (PMID 35741707, 2022). "TGFB-Beta/Smad3 signaling has been implicated in various obesity–inflammation pathways, including the endocrine organ secretion of adipocytokines (e.g., leptin and resistin)." (PMID 36142918, 2022). "Leptin is an adipokine produced by adipocytes and encoded by the obesity gene, and its level is associated positively with the size of adipocytes and body fat percentage." (PMID 36320802, 2022). "Serum leptin levels and leptin mutations are used in the diagnosis of congenital leptin deficiency and obesity." (PMID 35563103, 2022). "Very few results are available on the association between human leptin gene (LEP) variants and obesity traits in India." (PMID 36619235, 2022). "Leptin is an adipokine synthesized in adipocytes and encoded by the obesity (ob) gene with anorexigenic properties." (PMID 35757435, 2022). "Insensitivity to the action of leptin, termed “leptin resistance”, is a potential mechanism underlying the development of obesity." (PMID 36512575, 2022). "LEPR has six isoforms (A–F), which, along with leptin, are associated with obesity, with the first LEPR mutation being reported in North Africa (c.2598 + 1G>A)." (PMID 35563103, 2022). "An example of the complexity is supported by the observation that two adipokines associated with obesity, leptin, and adiponectin, are also up-regulated in asthma via a mechanism that remains to be elucidated." (PMID 35807067, 2022). "OSA, a kind of obesity-related sleep and breathing disorder, is known to be associated with increased leptin secretion." (PMID 36551211, 2022). "SOCS3 expression in obesity is associated with decreased energy expenditure, increased food intake, increasing adiposity, and insulin and leptin resistance." (PMID 35406000, 2022).
Obesity (continued). "Obesity can also cause leptin resistance, resulting in reduced breakdown of lipid oxidative products and ectopic fat deposition." (PMID 35371597, 2022). "This study was designed to analyse the polymorphisms in human leptin gene and to study the association of variants with the incidence of obesity among the population in Kerala." (PMID 36619235, 2022). "We conclude that the AG/AA polymorphisms in the leptin and adiponectin genes alter the serum levels of these adipokines and predispose to obesity." (PMID 35703718, 2022). "In our community-based study, we investigated leptin, which is considered a biomarker of obesity, in association with CKD in middle-aged and elderly people in northern Taiwan." (PMID 36619557, 2022). "The α-MSH analog setmelanotide is approved for some homozygous monogenic mutations (LEPR, MC4R, POMC, PCSK1) in the leptin–melanocortin pathway to treat severe obesity and is being studied for heterozygous mutations as well." (PMID 35447963, 2022). "Similar to the result obtained with AGRP-specific Trsp ablation, SclyAGRPKO mice were found to be less susceptible to HFD-induced obesity and maintained hypothalamic leptin sensitivity while on an HFD." (PMID 36499772, 2022). "Here, we observed that ponatinib is effective to ameliorate high-fat diet (HFD)-induced hyperlipidemia and NAFLD in leptin-deficient obesity mice model." (PMID 36457708, 2022). "Another study investigated the role of obesity-associated adipokine, leptin, in activating lung immune cells and inducing airway inflammation in asthma using Ob−/− leptin-deficient mice." (PMID 35888038, 2022). "Mice with a genetic mutation of 5-HT2CRs display leptin-independent hyperphagia, which leads to late-onset obesity, insulin resistance, and impaired glucose tolerance." (PMID 35163521, 2022). "First discovered in cloned obese mice, leptin deficiency due to homozygous mutations was shown to result in extreme obesity and infertility." (PMID 36379980, 2022). "These preliminary results encourage conducting basic studies to clearly identify the interrelationship between PLAC8 and LEPTIN and its involvement in preeclampsia and the associated obesity." (PMID 35252239, 2022). "POMC deficiency and LEPR deficiency are caused by genetic variants in the leptin-melanocortin signaling pathway and are characterized by early-onset severe obesity and hyperphagia." (PMID 35123544, 2022). "The mean serum leptin level showed a strong association with LEP + 19 A variant when compared to dominant “G” allele in both control (P=0.01) and obesity groups (P=0.004)." (PMID 36619235, 2022). "Structural variants of genes associated with BC and obesity, including LEP, LEPR, PON1, FTO, and MC4R, are associated with a higher or lower risk of BC." (PMID 36253742, 2022). "Despite there being over one million SNPs of the human genome, only a few specific SNPs, including those of LEP, have shown the potential to be associated with various conditions, including obesity and cancer." (PMID 35563103, 2022). "To determine the effect of obesity with leptin deficiency on endometriosis, we surgically induced endometriosis in 8-week old ob/+ or ob/ob female recipients of donor uterine fragments from control ob/+ or ob/ob uteri." (PMID 36140261, 2022). "Our results showed that carriers of rare heterozygous variants in the leptin-melanocortin pathway are predisposed to the early onset of obesity." (PMID 35574020, 2022). "In animal models, excessive leptin exposure early in life can lead to a state of persistent leptin resistance and obesity in adulthood while leptin deficiency can interfere with organ growth and neurodevelopmental outcomes." (PMID 35197933, 2022). "Obesity markers (leptin, neutrophil gelatinase-associated lipocalin (NGAL), retinol-binding protein 4 (RBP4), soluble intercellular adhesion molecule-1 (sICAM-1), and zinc alpha 2-glycoprotein (ZAG))." (PMID 35276788, 2022).
Obesity (continued). "Carriers of LEP rs2167270 and rs7799039 show a higher risk of obesity and insulinresistance and should reduce the intake of carbohydrates, especially from sweets and snacks." (PMID 35565885, 2022). "Homozygous pathogenic mutations in the leptin gene lead to a deficiency of biologically active leptin and cause severe early-onset obesity." (PMID 36121795, 2022). "A loss of hypothalamic LepR activity is the driving cause of hyperphagic obesity in the db/db mouse model and believed to contribute to both decreased satiety and increased leptin secretion in the state of obesity." (PMID 36111295, 2022). "Previously, LEP was sequenced and analyzed for variants that are potentially associated with the pathophysiology of obesity and obesity-related complications such as T2DM and hypertension." (PMID 35334523, 2022). "Several studies have reported the associations of human leptin gene with obesity, insulin resistance, and diabetes mellitus across different population." (PMID 36381191, 2022). "MiR-200 has also been found to be an important target for obesity, in that it is linked to the alteration of leptin and insulin signaling, specific to the upregulation of hypothalamic miR-200a." (PMID 36142918, 2022). "These mice have spontaneously developed a mutation in leptin, leading to increased food intake, obesity, and steatosis." (PMID 36187787, 2022). "High levels of leptin and low levels of adiponectin in the serum are associated with obesity and act as a risk for the development of CRC." (PMID 36429114, 2022). "The excessive accumulation of fat leads to dysregulation in secretion and metabolism of adipokines, including leptin and insulin which, thereby, develops obesity and associated complications." (PMID 36033946, 2022). "Obesity is closely associated with hypothalamic endoplasmic reticulum (ER) stress responsible for leptin resistance and perturbation of energy homeostasis." (PMID 36009315, 2022). "In general, rare mutations in LEP are associated with severe early obesity, through an effect on leptin signaling, leading to congenital leptin deficiency or leptin resistance." (PMID 35563103, 2022). "The present work, therefore, focuses on the evaluation of the association of clinical markers related to obesity and SNPs of the LEP, LEPR, POMC, PCSK1, and MC4R genes in a healthy Mexican population." (PMID 35741707, 2022). "Leptin and adiponectin concentrations have been shown to be positively and negatively associated with obesity, respectively." (PMID 35276805, 2022). "Despite studies indicating that genetic factors contribute to obesity and that no mutations in any one gene cause obesity in humans, several studies have reported extreme obesity due to a congenital deficiency in leptin synthesis." (PMID 35563103, 2022). "Leptin, a protein encoded by obesity genes, is mainly synthesized and secreted by body fat and is proportional to body fat mass." (PMID 36601002, 2022). "Diabetes, obesity, and inflammation seem to be associated with the development of peripheral leptin resistance, which causes impaired leptin signalling in the brain." (PMID 35510203, 2022). "Experimentally targeted STAT locus deletion in mice causes severe obesity due to probable induction of leptin resistance." (PMID 35388304, 2022). "These hypothalamic disorders contribute to leptin and insulin resistance, which are associated with the development of obesity." (PMID 36226318, 2022). "Obesity is linked to leptin and insulin resistance, and even though the mechanism and response to pharmacological administration differs, it is not surprising that resistance to another circulating metabolic regulator, FGF21, has been suggested." (PMID 36034414, 2022). "In a less severe mouse model of leptin deficiency, the burden of obesity and DM is related to a gut microbiota signature, in particular a reduction in a time-dependent manner of Akkermansia muciniphila abundance." (PMID 35409202, 2022).